CGAS (cyclic GMP-AMP synthase)
Diseases named in the same sentence as CGAS in open-access papers (continued):
Sharing a sentence is not in itself a finding about the gene and the disease.
infection (continued). "Thus, T-cell receptor-driven signalling and cytokine secretion dominate in vitro T-cell infection experiments, obviating virus-induced changes including cGAS/TRIM5 activation." (PMID 36289397, 2022). "Although the mechanism of nuclear cGAS inhibition is well elucidated, the role of nuclear cGAS in DNA sensing, especially in the settings of infection, is unknown." (PMID 35538147, 2022). "Notably, two S. Typhimurium genes sciK and dnaE were detected in cGAS compared to IgG controls, suggesting S. Typhimurium DNA also binds to cGAS during infection." (PMID 35604097, 2022). "cGas-/- mice are more susceptible to infection of several RNA viruses despite that many RNA viruses do not directly activate mammalian cGAS2." (PMID 36379959, 2022). "However, emerging evidence has linked the cGAS-cGAMP-STING pathway with autophagy and both pro-inflammation and anti-bacteria effects upon infection have been reported." (PMID 35846745, 2022). "The DNA damage from mutant infection activated the cGAS/STING pathway." (PMID 36514984, 2022). "During live infection, besides live bacteria and bacteria components, there were dead host cells in the lung that could release their DNA and activate the cGAS–STING pathway." (PMID 34512626, 2021). "• Restricts infection by activation of the immune response, via cGAS, after recognition of CA." (PMID 33868211, 2021). "PCV2 infection induces the immunosuppression of host, and leads to susceptibility of infected pigs to multiple pathogens, yet how PCV2 infection interferes cGAS-STING signaling to promote the infection of themselves and other DNA viruses is still poorly understood." (PMID 34543359, 2021). "Here, we show that the latency-associated protein UL138 inhibits the cGAS/STING/TBK1 innate immunity pathway during transfections and infections, in fully differentiated cells and incompletely differentiated myeloid cells, and with loss of function and restoration of function approaches." (PMID 34903048, 2021). "Second, cGAS can be activated by infection induced cell–cell fusion." (PMID 34578409, 2021). "This review briefly summarizes the research progress on how autophagy regulates the cGAS–STING pathway, regulating type I IFN production, with a particular focus on the crosstalk between autophagy and cGAS–STING signaling during infection by pathogenic microorganisms." (PMID 34926445, 2021). "Additionally, the coordination of signaling through TLR9 and cGAS pathways orchestrates production of type I IFN in response to infection with ectromelia virus (ECTV)." (PMID 34844429, 2021). "Our results suggested that HDAC6 may be a crucial player in mediating the degradation of ubiquitinated cGAS during diverse viruses’ infection, which needs to be explored in future." (PMID 34543359, 2021). "Initially, cGAS was described as a cGAMP synthase required for IRF3 dimerization following infection of murine fibroblast cells with herpes simplex virus type-1 (HSV-1), a DNA herpesvirus previously known to induce the expression of IFNs through the STING-IRF3 axis." (PMID 33708225, 2021). "Indeed, in both keratinocytes and macrophages, IFI16 cooperates with cGAS for STING activation upon infection." (PMID 33981307, 2021). "It is interesting to note that the absence of IFNAR signaling in mice does not increase their susceptibility to infection, whereas the absence of cGAS or STING slightly does increase their susceptibility to infection." (PMID 35011636, 2021). "In addition to a central role in innate immune defense against pathogen infection, recent studies also suggest a critical role of the cGAS‒STING pathway in metabolism." (PMID 34665236, 2021). "However, when we measured IFN-β protein levels at 0-, 8- and 24h post-infection by ELISA, we observed a complete loss of IFN-β in supernatants from both cGAS and STING KO macrophages." (PMID 34473814, 2021).
infection (continued). "The tegument protein layer of HCMV encodes a pp65 protein that is important for innate immune evasion (IFI16/cGAS-STING pathway) in the early stages of infection, but pp65 is also a T-cell target antigen and has been explored as a vaccine candidate with limited success." (PMID 34452332, 2021). "A recent study also showed that the cytosolic DNA sensor cGAS could recognize NETs and mediate immune cell activation during infection." (PMID 34158841, 2021). "In summary, for the first time, we demonstrate that DEV could succeed in escaping the cGAS-STNG-IRF7 signaling pathway in support of their long-time infection." (PMID 32537474, 2020). "Additionally, a component of poxviral lateral bodies expressed late in infection, F17, specifically modulates the cGAS-STING pathway to interfere with IRF-induced TI-IFN production." (PMID 33092186, 2020). "This early cleavage event in conjunction with replicative intermediates produced immediately upon infection could synergistically result in antagonism of cGAS dependent signaling, but only in the context of infection." (PMID 33057424, 2020). "A recent study showed that cGAS could sense mitochondrial damage during infection of dengue virus to start type I IFN responses." (PMID 31940818, 2020). "Moreover, the release of mitochondrial DNA into the cytoplasm during infection by dengue virus, a flavivirus, leads to cGAS activation." (PMID 32751803, 2020). "The cGAS-STING pathway protects against infections with viruses, bacteria, and protozoan parasites by sensing pathogenic DNA, infection-induced mitochondrial damage, bacterial proteins, virulence factors and metabolites, and bacteria-derived cyclic dinucleotides (CDNs)." (PMID 33329537, 2020). "Activation of the cGAS-STING pathway may promote the myeloid-biased differentiation of HSPCs to enhance the anti-infection reservoir of the immune system." (PMID 33329537, 2020). "The discovery that cGAS/STING signaling can directly regulate the transcription of MHC genes in macrophages provides further evidence linking PRR signaling with the activation of adaptive immunity during infection." (PMID 33633733, 2020). "As a result, phosphorylation of cGAS at this site leads to elevated HSV1 titers post‐infection." (PMID 32195086, 2020). "Combined with the previous knowledge that part of the cGAS/STING pathway is a target for DENV antagonism and the observation that MDDCs infected with DENV demonstrated a reduction in their ability to induce IFN-I and ISG15 mRNA, we proceeded to study if cGAS was impacted during infection." (PMID 32899347, 2020). "Interestingly, similar to the infection with cytopathogenic RNA viruses, stimulation of the cGAS–STING axis in human myeloid cells induces a cell death program initiating K+ efflux upstream of NLRP338." (PMID 31024004, 2019). "Importantly, early after infection the cGAS-STING pathway was induced by both attenuated and virulent ASFV, but later on, was effectively inhibited only by virulent Armenia/07." (PMID 30918080, 2019). "Furthermore, recent studies highlighted the importance of cytosolic mtDNA in cGAS-mediated antiviral immune responses after infection with certain RNA viruses, such as VSV, lymphocytic choriomeningitis virus (LCMV), Sindbis virus, and dengue virus." (PMID 31604929, 2019). "Armenia/07 inhibits the cGAS-STING pathway by impairing STING activation during infection." (PMID 30918080, 2019). "Infection with the CHa strain induced significantly increased expression of cGAS, RIG-I, MDA5, IRF7, IFN-β, and MX in monocytes/macrophages at 6 hpi, and these levels were higher than those observed in mock-treated cells but lower than those in cells infected with CHv strain." (PMID 32063900, 2019). "In view of the importance of the cGAS–STING pathway in the production of type I IFNs upon infections by DNA virus, we hypothesize that the type I IFN gene expression induced by ECTV might be through cGas and Sting." (PMID 29963044, 2018).
infection (continued). "In addition, the cGAS–STING pathway is emerging as the dominant cytosolic DNA-sensing pathway in infections by DNA viruses." (PMID 29963044, 2018). "Finally, recent in vitro infection models suggest that the DNA sensor, cGAS, detects chlamydial DNA which leads to expression of IFN-β via STING." (PMID 28529959, 2017). "In addition, cGas-/- mice are more vulnerable to lethal infection after exposure to herpes simplex virus 1 (HSV-1) than wild-type mice." (PMID 28273161, 2017). "Because PRRs like OAS and cGAS act as crucial sentinels of infection, we set out to compare mechanisms by which they might adapt to pathogen-encoded inhibitors." (PMID 25942676, 2015). "The cyclic GMP‐AMP synthase (cGAS) and stimulator of interferon (IFN) genes (STING) pathway serves as a main effector of cell sensing pathogenic double‐stranded (ds) DNAs and self‐aberrant DNAs, playing a critical role in anti‐infection and antitumor immune responses." (PMID 41395239, 2025). "Furthermore, we observed potent protein-S-nitrosylation of pp65 at later times during infection, whereas one could envision that this host-directed modification would need to be induced earlier for maintaining cGAS/STING induction." (PMID 40243337, 2025). "Similarly, while microbial DNA is typically safeguarded within nucleoid-like structures, the disruption of microbial cellular barriers during infection can expose this DNA to cytosolic cGAS detection, subsequently activating the STING pathway and triggering immune responses." (PMID 41438738, 2025). "Indeed, cGAS detects HCMV lytic infection of endothelial cells and triggers a type I IFN response." (PMID 40872823, 2025). "Alternatively, infection-induced sensing of cellular DNAs such as mitochondrial DNA that have leaked into the cytoplasm, which has been observed for other viruses, could also contribute to the activation of cytoplasmic cGAS in HCMV infected cells." (PMID 38932169, 2024). "Additionally, RTP4 may contribute to the suppression of type I IFN induction during the cyclic GMP-AMP synthase (cGAS)-stimulator of interferon genes (STING) pathway following pathogen infection, functioning as a negative regulator." (PMID 39769444, 2024). "Thus, cGAS phosphorylation at this site leads to elevated HSV‐1 titers after infection." (PMID 38525112, 2024). "Thus, it is possible that nuclear HCMV genomes, which are initially histone-free, could also serve directly or indirectly as a ligand for cGAS activation during infection." (PMID 38932169, 2024). "However, a product consistent with the cGAS 3C cleavage product could be detected during infection with the Lpro-deficient FMDV, suggesting the 3C cleavage of cGAS during infection." (PMID 38509419, 2024). "Moreover, the consistent phenomena in HSV-1-infected A549 cells with IFI16−/−, indicating that IFI204 might facilitate cGAS-STING DNA sensing pathway that leads to IRF3 activation during the infection of HSV-1." (PMID 38195584, 2024). "Interestingly, HPVs antagonize the cGAS/STING DNA-sensing pathway to facilitate infection." (PMID 36928117, 2023). "However, during EV-A71 infection, cGAS-STING activation was attenuated." (PMID 36823147, 2023). "In addition, VACV∆E5R infection of WT BMDCs induced cGAMP production, indicating cGAS activation." (PMID 37217469, 2023). "Macrophages from cGAS- and STING-deficient mice were severely impaired in producing proinflammatory cytokines (and type I IFNs) in response to Legionella pneumophila, and the same defect was observed when the infection was performed on cells from patients carrying the HAQ variant of STING." (PMID 37261352, 2023). "Various studies have demonstrated that cGAS not only recognizes a wide range of microbial DNA but also senses mitochondrial DNA (mtDNA) and cellular nuclear DNA (nDNA) aberrantly localized to the cytosol after infection or under stress or pathological conditions." (PMID 37932533, 2023).
infection (continued). "Similarly, infection of WT or cGAS knockout THP1 monocytes that express an ISG54 promoter-driven Lucia Luciferase reporter demonstrated that responses to iF17 infection occurred at later times of infection and in a cGAS-dependent manner." (PMID 38036506, 2023). "Notably, a recent work demonstrated that cGAS/STING signaling is critical to mount an anti-T. gondii immune response in a mouse infection model, which was enhanced by the dense granule protein GRA15 secreted by T. gondii in a STING- and TNF receptor associated factor (TRAF)-dependent manner." (PMID 35108342, 2022). "Together, these data suggest that early STING activation to induce IFN production may be beneficial, while later in infection, pro-inflammatory cytokines produced by epithelial cells, endothelial cells, and macrophages via the cGAS-STING pathway provoke pathological effects." (PMID 36419185, 2022). "In addition, we also showed that bacterial DNA was enriched in cGAS during infection, which may contribute to cGAS activation." (PMID 35604097, 2022). "To test whether the nucleic acid-sensing pathways have a function in host defense against VACV∆C7L infection, we performed intranasal infection of VACV∆C7L in cGas−/−, Sting1gt/gt (which lack functional STING), Ifih1−/− (MDA5 knockout), Ifih1−/−Sting1gt/gt or Irf3−/− mice." (PMID 35351885, 2022). "In addition, STING−/− mice derived PMs also exhibited significant lower type I IFN response during S. Typhimurium infection at 2 h.p.i and 4 h.p.i, suggesting the cGAS-STING pathway was also involved in the initial activation of type I IFN response during infection." (PMID 35604097, 2022). "In particular, mtDNA stress induced by herpes simplex virus 1 (HSV-1), a DNA virus, infection results in both hyperfusion of mitochondria and release of mtDNA into the cytosol, and the consequent priming of innate immune responses via the cytosolic DNA sensor cGAS." (PMID 34648591, 2021). "During the potent activation of innate immunity signaling observed upon infection, DNA from the invading microorganism is the likely source of cGAS activation, but where might the DNA required to co-stimulate cGAS activity upon the experimental perturbation of the RQC pathway come from?" (PMID 34111399, 2021). "Indeed, as we guessed that PCV2 did inhibit type I interferon expression via suppressing cGAMP production by gC1qR-mediated catalytic activity inhibition in the early phase of infection, and gC1qR/HDAC6/autophagy regulator axis-mediated cGAS degradation in the late phase of infection." (PMID 34543359, 2021). "Finally, modulation of the immune environment by CDT upon infection may vary with tissue or even cell type, as evidenced with cGAS downregulation in HCECs." (PMID 34308492, 2021). "As previously observed, the loss of cGAS (Fig EV5B) or MAVS (Fig EV5C) had no impact on HIV‐1 infectivity suggesting sensing does not contribute to the inhibitory effect of PF74 in these single round infections." (PMID 32852081, 2020). "As we observed a slight decrease in DNA stimuli-dependent type-I IFN transcripts in the UVC conditions and because the decrease in cGAS occurs very early during the infection, we hypothesized that the viral factor responsible for cGAS degradation is a component of the virion." (PMID 33057424, 2020). "Thus, degradation of cGAS could be mediated partially by nsP4, but only when the host protein is degraded by the proteasome in the context of infection." (PMID 33057424, 2020). "In addition, infection of transgenic mice has shown that mice lacking cGAS were slightly more susceptible to high doses of VACV." (PMID 32948585, 2020). "However, an explanation for these results may again stem from the ability of HSV-1 to downregulation IFI16 and cGAS expression and/or inhibit their signaling pathways in human microglia following infection." (PMID 33042875, 2020).
infection (continued). "Even when more studies are warranted before a definitive antiviral or proviral role can be ascribed to EREs in mammalian systems during infection, we hypothesize that future studies may show more host nucleic acids can act as agonists for the cGAS/STING pathway during RNA virus infection." (PMID 32899347, 2020). "Our study reveals that the cGAS-STING cascade contributes to antibacterial defense against L. pneumophila in mice and men, and provides important insight into how the common HAQ TMEM173/STING variant affects antimicrobial immune responses and susceptibility to infection." (PMID 29298342, 2018). "This may explain why mice lacking DDX41 or cGAS show only 5-fold-higher infection than wild-type mice; even STING-deficient mice show only 10-fold-higher infection." (PMID 29871919, 2018). "Notably, the secretion of IFN-β in the serum of all mice through a subcutaneous infection was undetectable in our study, suggesting the cGas–Sting pathway might be responsible for local type I IFNs production at the early stage of ECTV infections." (PMID 29963044, 2018). "Studies involving WNV have illustrated that cGAS (cyclic GMP‐AMP synthase) knockout mice were more susceptible to infection and suggested that in the absence of cGAS, base levels of certain antiviral ISGs are reduced, causing the cell to be more permissive to infection." (PMID 28273394, 2017). "Analyses of cGAS knockout mice reveal its essential roles in fibroblasts, macrophages, and dendritic cells in response to various DNA stimuli transfections and DNA pathogens (DNA viruses, retroviruses, Listeria monocytogenes and Mycobacterium tuberculosis) infection." (PMID 28273161, 2017). "Under physiological conditions, cellular DNA is confined to the nucleus or mitochondria, and the cGAS-STING pathway is activated only upon sensing viral or bacterial DNA, inducing IFN-I response to protect neighboring cells from infection." (PMID 40351606, 2025). "The recent study has shown that PCV2 can inhibit the activation of the cGAS-STING signaling pathway to block the production of type I interferon IFN-β, thus promoting PCV2 infection." (PMID 40742129, 2025). "These processes not only compromise cellular bioenergetics but also influence immune signaling cascades, such as cGAS-STING and NLRP3 inflammasome pathways, thereby shaping infection outcomes." (PMID 41404367, 2025). "At 2, 6, and 12 h post-infection (hpi), the transcriptional levels of key genes of cGAS/STING signaling pathway, including cGAS, STING, TBK1, IRF3, IRF7, and IFN-β were evaluated." (PMID 39601590, 2025). "Upon infection, OV activates two parallel pathways: the left axis represents the ICD pathway, leading to the release of DAMPs, while the right axis shows the cGAS-STING pathway, upregulating type I interferons and CXCL10." (PMID 40977706, 2025). "The substantial decrease of IFN-I production in BTV-infected cells correlates with cGAS and STING degradation observed during infection." (PMID 39836220, 2025). "Compared to infection with ASFV-Δ4R, infection with ASFV-WT increased the interaction between endogenous cGAS and TOLLIP in PAMs." (PMID 40618140, 2025). "The cyclic GMP-AMP synthase (cGAS)–type I interferon (IFN-I) pathway detects cytoplasmic DNA, which typically signals infection and triggers immune defenses against viruses and bacteria." (PMID 40282455, 2025). "Infection with ancestral SARS-CoV-2 was performed at a multiplicity of infection (MOI) of 5 and cells were treated with the specific cGAS inhibitor (G140) after 2 h post infection (hpi)." (PMID 41139159, 2025). "With infection, expression of certain PRRs in platelets increased (TLR9, RIG-I, and CGAS), while in leukocytes, they decreased (TLR6, TLR8)." (PMID 40825056, 2025). "Fifteen hub genes of cGAS-STING signaling pathway were selected to investigate the differential expression patterns among CL, SL, and RL following infection." (PMID 40356894, 2025).